BMP2 (bone morphogenetic protein 2)
Diseases named in the same sentence as BMP2 in open-access papers (continued):
Sharing a sentence is not in itself a finding about the gene and the disease.
liver (2 papers, 2012 to 2024). "Therefore, the increased mRNA expression of BMP2 we observed after AFB1 treatments of HHL-16 cells might indicate a novel mechanism in aflatoxin-induced chronic liver injury." (PMID 38468450, 2024). "Recent developments in the role of BMP2/4 in tumorigenesis and Gremlin’s role in angiogenesis may provide novel directions to elucidate the mechanism by which Gremlin can induce proliferation in lung AD." (PMID 22870311, 2012).
colon polyps (1 paper, 2025). "We identified 25 genome-wide significant loci for CRC and colon polyps, including three novel loci in East Asian populations: BET1L (rs12226698, 11p15.5), OAS1 (rs2525858, 12q24.13), and BMP2 (rs4813802, 20p12.3)." (PMID 40303978, 2025). "In this analysis of CRC and colon polyps, we identified 25 genome-wide significant loci, including three novel loci in East Asian populations: rs12226698 at 11p15.5 (BET1L), rs2525858 at 12q24.13 (OAS1), and rs4813802 at 20p12.3 (BMP2)." (PMID 40303978, 2025).
endocrine disorders (1 paper, 2023). "The identification of common pathogenic mechanisms in monogenic and endocrine disorders associated with OPLL/DISH, and the development of targeting therapeutics for other relevant pathways such as ACVR1, COL11A2, COL6A, BMP2,4,9, and TGF-β1 are remaining important questions to be addressed." (PMID 37530996, 2023).
heart diseases (1 paper, 2024). "Growing evidence has demonstrated that BMP2 is involved in the systematic inflammatory response to various heart diseases." (PMID 39334820, 2024).
vascular disorder (1 paper, 2020). A general term used to describe any disease affecting blood vessels]. "We investigated the effect of bone morphogenetic protein (BMP)‐2 in controlling VSMC phenotype and vascular disorder progression." (PMID 31737960, 2020). "A thorough understanding of the precise relationship between KDM1A and BMP‐2 will allow us to develop effective strategies for targeted local delivery of KDM1A‐based agents with therapeutic potential against neointimal hyperplasia and other vascular disorders." (PMID 31737960, 2020).
BMP2 also shares sentences with these, for which no sentence is quoted: multiple myeloma (7 papers); ovarian tumor (4); squamous cell carcinoma (4); Chronic Osteomyelitis (3); metabolic disease (3); osteogenesis imperfecta (3); type 1 diabetes (3); Adenovirus infections (2); ameloblastoma (2); coronary atherosclerosis (2); enthesopathy (2); injury (2); kidney disease (2); Legg-Calve-Perthes disease (2); metastatic melanoma (2); Myelopathy (2); neurodegenerative disease (2); pulmonary hypertension (2); pulpitis (2); rectal adenocarcinoma (2); scoliosis (2); viral infection (2); Acidosis (1); Adamantinomatous Craniopharyngioma (1); adenomyosis (1); Alzheimer disease (1); aneurysm (1); arterial diseases (1); arteriosclerosis (1); atrial septal defect (1).
A further 91 diseases each share a sentence with BMP2 in 1 paper.